LAPTM4B (lysosomal protein transmembrane 4 beta)
Diseases named in the same sentence as LAPTM4B in open-access papers (continued):
Sharing a sentence is not in itself a finding about the gene and the disease.
tumor (continued). "In this study, we first screened for transcription factors that bind to the 19‐bp polymorphism sequence of the LAPTM4B promoter region and found that AP4 could promote HCC tumour growth, metastasis but reduce chemotherapy sensitivity by positively regulating LAPTM4B expression." (PMID 29337428, 2018). "Moreover, it was indicated that LAPTM4B could increase the proliferation and metastasis of tumor cells, reduce apoptosis, and assist drug resistance, which involved in activated PI3K/AKT and Ras-MAPK signaling pathways." (PMID 28476037, 2017). "Immunohistochemical analysis revealed marked upregulation of both LAPTM4B and ATP1A1 in post-resistance tumor samples compared to matched pre-treatment samples from the same patients." (PMID 41362742, 2026). "The intersection of LGR5+ and LAPTM4B+ stem‐like cells provide a basis for CRC stratification, leading to the CSS classification, which delineates four tumor subtypes with distinct biological and clinical attributes." (PMID 40661135, 2025). "Further analysis from GEO (GSE#31210) showed that the expression of LAPTM4B and SLC7A11 was significantly increased in tumor samples compared to normal tissue." (PMID 38902268, 2024). "IHC staining of tumor tissues demonstrated that CAY10683 effectively suppressed HDAC2 expression, attenuating both HDAC2-induced autophagy and proliferation, as well as LAPTM4B expression." (PMID 39147759, 2024). "Initially, we analyzed publicly available databases TCGA and GTEx to assess the relevance of LAPTM4B and SLC7A11 in tumor samples compared to adjacent normal tissue." (PMID 38902268, 2024). "Patients with AFP > 20 ng/ml, age>50, tumor diameter>6 cm, early recurrence (+), and advanced BCLC stage exhibited LAPTM4B up-regulation (P < 0.05)." (PMID 38388484, 2024). "To further validate these findings in vivo, we established a xenograft tumor model and observed that the reduced tumor volume in the HDAC2 knockdown group was rescued upon overexpression of LAPTM4B." (PMID 39147759, 2024). "Therefore, LAPTM4B up-regulation might promote tumor angiogenesis." (PMID 38388484, 2024). "LAPTM4B-produced CXCL8 attracts MDSCs to TME and triggers neutrophil MDSCs to extrude NETs, facilitating tumor cell nesting." (PMID 38388484, 2024). "In MDA‐MB‐231, we found a significant upregulation of LAPTM4B, RAB40C, MMP3, and downregulation of PRKCZ after tumor treatment with doxorubicin." (PMID 34109737, 2022). "Chi-square test analysis showed that the high expression of LAPTM4B was closely related to the histological subtype of NPC patients and tumor-node-metastasis (TNM) staging." (PMID 32651973, 2021). "Human LAPTM4A has 46% amino acid homology with human LAPTM4B, another LAPTM family member involved in tumor progression and lysosomal ceramide transport." (PMID 30660999, 2019). "In the advanced tumor stage, 84% and 57% of patients, while in lower stage group 30% and 46% of patients, were having elevated expression of HIF-1α, MDR1 and LAPTM4B." (PMID 30746305, 2019). "High levels of LAPTM4B, VEGF, and nuclear survivin were found in cases where factors related to tumor progression were present, such as tumor sizes >2 cm, TNM stage II+III and lymph node metastasis." (PMID 28476037, 2017). "Using an unbiased high-content drug screen, we identified several small molecules that selectively inhibit LAPTM4B, and demonstrated that combination treatment with copanlisib and EGFR-TKIs produces robust anti-tumor effects in vitro and in vivo with negligible side effects." (PMID 41362742, 2026). "Notably, LAPTM4B and ATP1A1 expression levels were positively correlated across tumor specimens, further supporting a cooperative role for these two proteins." (PMID 41362742, 2026). "A simple method leveraging the relative expression of LAPTM4B and LGR5 within tumor tissues may provide an accurate prediction of disease progression." (PMID 40661135, 2025).
tumor (continued). "In LAPTM4B-overexpressing patients, CD274 (PD-L1) overexpression on tumor surface suggests that treatment with PD-L1 antibodies may have therapeutic efficacy." (PMID 38388484, 2024). "We analyzed the data from GEO database (GSE125645, GSE161407) and EWAS data hub, and found that LAPTM4B methylation percentage is not significantly altered in OS tumor tissues compared with normal control tissues." (PMID 37147294, 2023). "Thus, the in silico predictions suggest that, as the most common NPC tumor subtype, HNSC shows differential expression of LAPTM4B." (PMID 32651973, 2021). "However, there has been reported evidence of circulating tumor cells (CTCs) to be another contributing factor of HIF-1, MDR1 and LAPTM4B in patient’s blood." (PMID 30746305, 2019). "The data showed that high LAPTM4B-35 expression had a significantly negative influence on DFS in patients with HPV positive tumours (p = 0.0643 [Log Rank], p = 0.0453 [Gehan-Breslow])." (PMID 31827181, 2019). "Consistent with tumour growth results, the LNA− tumour group with lowest intratumoral LAPTM4B expression showed the lowest Ki‐67 expression, while the L+A− group tumour partially reversed the expression of Ki‐67 by overexpression of LAPTM4B." (PMID 29337428, 2018). "LAPTM4B-35 did not express in normal gastric mucosa, but expressed in the intestinal metaplasia、dysplasia lesion (Data was not shown) and tumor cells, and mainly localized within the cytoplasm or on the cell membrane." (PMID 25849595, 2015). "Moreover, combined quantification of LAPTM4B and LGR5 expression demonstrated superior predictive power for tumor progression compared to individual markers, underscoring the synergistic influence of heterogeneous stem‐like cell populations on patient outcomes." (PMID 40661135, 2025). "Interestingly, erastin treatment significantly reduced the tumor size in the mice injected with LAPTM4B KO cells, but not in those injected with WT A549 cells." (PMID 38902268, 2024). "Moreover, in these tumor samples from nude mice, the expression of LAPTM4B positively correlated with expression of SLC7A11, but not GPX4." (PMID 38902268, 2024). "LAPTM4B expression was significantly different between tumor and normal tissues (p = 8.16e-09)." (PMID 38388484, 2024). "Since high LAPTM4B-35 expression is associated with advanced tumour stage and significantly worse DFS as well as a higher recurrence rate, LAPTM4B-35 could serve as a negative prognostic marker in patients with HNSCC." (PMID 31827181, 2019). "Moreover, LAPTM4B under hypoxic cellular adaptation, chip in a compelling part towards cell proliferation furthering tumor expansion rather than simply being upregulated as a secondary outcome of speedy tumorigenesis." (PMID 30746305, 2019). "LAPTM4B is a type III transmembrane protein with four putative transmembrane regions and highly expressed in LAC tissues, so we test whether serum levels of LAPTM4B could be used as a tumor marker in LAC." (PMID 30940109, 2019). "We then examined whether there were differences in LAPTM4B-35 expression patterns between primary tumours and lymph node metastases." (PMID 31827181, 2019). "Although some research has shown that c‐myc works together with AP4 to regulate tumour pathogenesis or that AP4 regulates the Wnt signalling pathway, which also involves c‐myc, our report is the first to show that AP4 also regulates c‐myc by affecting LAPTM4B expression." (PMID 29337428, 2018). "Only in tumor tissue were PF4 and LAPTM4B significantly increased without comorbidities." (PMID 37176055, 2023).
neurological disease (1 paper, 2026). "Lysosomal-associated protein transmembrane (LAPTM) family members-LAPTM4A, LAPTM4B, and LAPTM5-regulate lysosomal integrity, autophagy-lysosome flux, lipid homeostasis, and immune signaling, pathways increasingly implicated in neurological disease." (PMID 41666016, 2026).
reproductive diseases (1 paper, 2022). "Previous studies have reported that LAPTM4B is expressed in the reproductive organs and reproductive diseases in bovine or human." (PMID 35186931, 2022).
LAPTM4B also shares sentences with these, for which no sentence is quoted: colorectal cancer (5 papers); renal clear cell carcinoma (3); Hypertension (2); melanoma (2); acute lymphoblastic leukemia (1); adenocarcinoma (1); bladder cancer (1); Colorectal and (1); dysplasia (1); essential thrombocythemia (1); Ewing sarcoma (1); glioblastoma (1); idiopathic pulmonary fibrosis (1); leiomyosarcoma (1); lymphoma (1); metastatic disease (1); oesophageal cancers (1); pancreatic carcinoma (1); pancreatic ductal adenocarcinoma (1); rectal cancer (1); Stroke (1); synovial sarcoma (1); triple-negative breast carcinoma (1); uterine cancer (1).